ERMAP (erythroblast membrane associated protein (Scianna blood group))
Description:
Possible role as a cell-adhesion or receptor molecule of erythroid cells.
Synonyms: RD; SC; BTN5; PRO2801
Tractability: Antibody: UniProt places it where antibodies can reach, with high confidence; its Gene Ontology location is reachable by antibodies, with high confidence; UniProt predicts a signal peptide or a membrane-spanning region.
Gene: Protein-coding gene on chromosome 1 (42,817,078 to 42,845,907, forward strand). Ensembl gene ENSG00000164010.
Subcellular location: Cell membrane; Cytoplasm
Subcellular location (Human Protein Atlas): Golgi apparatus; Cytosol
Gene Ontology:
Molecular function: protein binding; signaling receptor binding
Biological process: regulation of cytokine production; T cell receptor signaling pathway
Cellular component: cytoplasm; cytosol; plasma membrane; external side of plasma membrane
Genetic constraint (gnomAD): Loss-of-function variants: 32 observed, 47.1 expected, observed/expected ratio (o/e) 0.68, 90% interval 0.51 to 0.91. The upper end of that interval is the gene's LOEUF score, 0.91, which puts it in group 3 of 6, group 1 being the genes least tolerant of losing a copy. Missense variants: 498 observed, 559.91 expected, observed/expected ratio (o/e) 0.89, 90% interval 0.83 to 0.96. Synonymous variants: 195 observed, 225.01 expected, observed/expected ratio (o/e) 0.87, 90% interval 0.77 to 0.98.
Homologues: Orthologues: chimpanzee ERMAP (99% identical), macaque ERMAP (92% identical), mouse Ermap (74% identical), rabbit ERMAP (70% identical), rat Ermap (70% identical), rat Zfp691 (70% identical), pig ERMAP (68% identical), dog ERMAP (63% identical). Paralogues in human: BTN1A1 (36% identical), BTN2A2 (36% identical), BTN2A1 (35% identical), BTN3A3 (35% identical), BTNL9 (33% identical), BTN3A1 (32% identical), BTNL8 (28% identical), BTNL3 (27% identical), BTNL2 (18% identical), BTN3A2 (14% identical), MOG (13% identical), CD276 (11% identical), and 3 more.
Diseases named in the same sentence as ERMAP in open-access papers:
ERMAP is named in the same sentence as 8 diseases in open-access papers, as found by Europe PMC text mining. Sharing a sentence is not in itself a finding about the gene and the disease. The quoted sentences say what the papers report.
cognitive decline (1 paper, 2021). "Taken together, our results suggest that administration of anti-ERMAP mAb into AD mice leads to clearance of Aβ plaques and reversal of cognitive decline." (PMID 34774090, 2021).
tumor (4 papers, 1996 to 2025). "Further mechanistic insights revealed that this phagocytic capacity depends on the formation of a bridging complex involving erythroid membrane-associated protein (ERMAP) expressed on tumor cells and galectin-9 on Kupffer cells." (PMID 41163402, 2025). "In contrast, patients with insufficient expression of SORBS2, PAM, ZFAT, DOCK7, ERMAP, BTF3, and GUSB in the tumor tissues had shorter survival duration than patients in the high-expression group." (PMID 37315301, 2023).
cancer (3 papers, 2021 to 2024). A tumor composed of atypical neoplastic, often pleomorphic cells that invade other tissues. "Galectin‐9 and transmembrane receptor dectin‐2, both on Kupffer cells, formed a bridging complex with ERMAP (erythroid membrane‐associated protein), expressed on various cancer cells, to induce the detection and phagocytosis of cancer cells by Kupffer cells." (PMID 39494816, 2024). "On the contrary, high expression of four genes, i.e., KEL, GCNT2, P1 and ERMAP, was associated with a higher cancer grade in LGG and HNSC." (PMID 35955933, 2022). "This is consistent with our previous report that anti-ERMAP Ab enhance macrophage phagocytosis of cancer cells." (PMID 34774090, 2021). "We have previously reported that anti-ERMAP polyclonal Ab can enhance macrophage phagocytosis of cancer cells." (PMID 34774090, 2021).
ERMAP also shares sentences with these, for which no sentence is quoted: Alzheimer disease (1 paper); cardiovascular disease (1); colorectal adenoma (1); colorectal cancer (1); Infertility (1).